TRIP13 (thyroid hormone receptor interactor 13)
Diseases named in the same sentence as TRIP13 in open-access papers (continued):
Sharing a sentence is not in itself a finding about the gene and the disease.
tumor (continued). "Moreover, it is necessary to study the anti-tumor activity of small molecule inhibitors targeting TRIP13 to determine whether TRIP13 is a potential target for CRC therapy." (PMID 35075117, 2022). "Among the top 20 hub genes, only the Hormone Receptor Interactor 13 (TRIP13) expression increased continuously from normal tissue to polyp to early-stage tumor to the late-stage tumor in the GSE41258 dataset, suggesting that TRIP13 might play an essential part in tumor progression." (PMID 35075117, 2022). "Furthermore, reduced TRIP13 expression curbed tumor metastasis and growth in hepatocellular cancer." (PMID 32694945, 2020). "For instance, TRIP13 could accelerate tumor growth in colorectal cancer." (PMID 32694945, 2020). "Thus, elevated TRIP13 promotes tumor cell proliferation, migration, and invasion in HCC cells." (PMID 31533816, 2019). "Meanwhile, few genes were uniquely expressed in TERT altered tumours; amongst these were IRX3, SDK1 and TRIP13." (PMID 40097403, 2025). "Conversely, a strong positive correlation was discovered between TRIP13 expression and THCA tumor samples." (PMID 40441196, 2025). "Thyroid hormone receptor interactor 13 (TRIP13) is an ATP enzyme that is overexpressed in a variety of tumors and is involved in tumor drug resistance." (PMID 40438586, 2025). "Meanwhile, few genes were uniquely expressed in TERT-altered tumours but included IRX3, SDK1 and TRIP13." (PMID 38978571, 2024). "The functions of TRIP13 on the proliferation of gastric malignancy were investigated by MTT, flow cytometry, colony formation experiment, and nude mouse tumor formation experiment." (PMID 37432513, 2023). "Our analysis showed that TRIP13 protein levels were significantly correlated with the individual’s alpha-fetoprotein (AFP) level, tumor number, and incomplete encapsulation (all P < 0.05)." (PMID 37740123, 2023). "The protein levels of TRIP13, YWHAE, and p-ERK were significantly higher in tumor tissues than in normal tissues." (PMID 38012658, 2023). "TRIP13 promotes CRC cell growth, proliferation, invasion, migration and subcutaneous tumor formation." (PMID 35114976, 2022). "Using siRNA or lentivirus to knock down TRIP13, we tested HCC cell and tumor growth in vitro and in vivo." (PMID 35517402, 2022). "The TRIP13 mRNA and protein expression were also significantly higher in the CRC cells, consistent with the results in tumor tissues." (PMID 35075117, 2022). "The oncogenic role of TRIP13 was confirmed in vitro and in vivo, and TRIP13 was related to the TNM tumor stage, CEA, and CA19–9 level in CRC patients." (PMID 35075117, 2022). "We identified that mRNA and protein levels of TRIP13 increased in CRC cells and tumor tissues with tumor progression." (PMID 35075117, 2022). "miR-4693-5p was significantly downregulated in CRC tumor tissues and bound to the 3′ untranslated region (3′UTR) of TRIP13, downregulating TRIP13 expression." (PMID 35075117, 2022). "HMGA1 facilitated pCCA proliferation, migration, and invasion by promoting tumor stemness and the EMT, which required the involvement of TRIP13." (PMID 33648560, 2021). "TRIP13 participated in several cancer-related pathways and the oncogenic potential in tumorigenesis may be likely involved in epigenetic regulation, miRNA-target interaction and the degree of aneuploidy, as well as the immune mediation in the tumor microenvironment." (PMID 34066132, 2021). "Similar to previous studies, SPP1, MTHFD2, TRIP13, MKI67, MMP9, and KLF4 were some of the most clinically valuable tumor markers, especially in CC and EC." (PMID 34834529, 2021). "Specially, high expression of TRIP13 in GBM was enriched in the microvascular proliferation, which is important for the tumor progression." (PMID 34066132, 2021).
tumor (continued). "With bioinformatics and in vitro/vivo experiments, we showed that HMGA1 induced tumor cell stemness and epithelial-mesenchymal-transition (EMT), and thus facilitated proliferation, migration and invasion by promoting TRIP13 transcription." (PMID 33648560, 2021). "There was higher expression of TRIP13 in CRC, and TRIP13 interacted with YWHAZ, which mediates G2-M transition and epithelial-mesenchymal transition to promote tumor growth." (PMID 33193642, 2020). "To confirm the role of TRIP13 in the EMT of CRCs, we performed western blot analysis using lysates of subcutaneous tumor xenografts of HCT116p53‐wt,MSI cells and probed for the epithelial marker, E‐cadherin, and the mesenchymal markers, N‐cadherin, and Snail." (PMID 33037736, 2020). "TRIP13 overexpression in CRCs correlates with expression of carcinoembryonic antigen (CEA), carbohydrate antigen 19‐9 (CA19‐9), and tumor stage (pTNM)." (PMID 33037736, 2020). "Mechanistically, TRIP13 interacted with ACTN4 and positively regulated its expression, thus activating the AKT/mTOR pathway to drive tumor progression." (PMID 31533816, 2019). "Differential gene expression analysis revealed 3155 DEGs (differentially expressed genes), among which six AAA ATPase genes (TRIP13, CHTF18, RFC4, ATAD2, FIGNL2, ATAD5) were significantly overexpressed in tumor samples compared to levels in normal samples." (PMID 31533816, 2019). "Functionally, elevated TRIP13 facilitated cell proliferation, migration, invasion, and promoted cellular epithelial–mesenchymal transition (EMT) in vitro, while promote tumor growth and lung metastasis in vivo." (PMID 31533816, 2019). "In this study, we used multiple methods to demonstrate that TRIP13 can promote CRC cell proliferation, migration, and invasion in vitro and subcutaneous implanted tumor formation in vivo, and it predicted poor survival of CRC patients." (PMID 29540729, 2018). "Tumor tissues and adjacent normal tissues from 52 HCC patients were collected, and the mRNA expression of TRIP13 was analyzed." (PMID 30564064, 2018). "We also found that TRIP13 promoted CRC cell proliferation, invasion and migration in vitro and subcutaneous tumor formation in vivo." (PMID 29540729, 2018). "The same study that used a chick chorioallantoic membrane (CAM) assay suggested that the overexpression of human TRIP13 in mouse fibroblasts NIH/3T3 cells resulted in focus formation, cell proliferation, and tumor growth in vivo." (PMID 28157697, 2017). "In patients with a large main tumour size, the expression of HSPB1 and TRIP13 was increased compared to patients with a small main tumour size." (PMID 28266596, 2017). "TRIP13 is a thyroid receptor interacting protein whose gene shows copy number changes in 68% of 19 early stage NSCLC tumour samples." (PMID 22075945, 2012). "TRIP13 and IGF2BP3, which promote tumour growth, were also highly differentially accessible." (PMID 40946111, 2025). "In addition, TRIP13 shRNA inhibits the proliferation of CRC cells and tumor growth of xenograft CRC mice." (PMID 35075117, 2022). "To determine whether this newly discovered mechanism also extended to other tumor entities beyond HCC, we determined the effects of Trip13 KD in different tumor cell lines." (PMID 36031387, 2022). "Blocking of this axis, EMT, NF‐κB and Wnt/β‐catenin signalling by DCZ0415 reduced CRC progression, indicating that DCZ0415 is a potential inhibitor of CRCs exhibiting TRIP13 overexpression and suggests a valid future therapeutic strategy for CRC tumours overexpressing TRIP13." (PMID 35194944, 2022). "The TRIP13 mRNA and protein expression distinctly increased in tumor tissues of 82 CRC patients compared to non-cancerous tissues." (PMID 35075117, 2022). "Xenografts were established with HMGA1-overexpressing stable cells with or without TRIP13 knockdown, showing that TRIP13 knockdown significantly reduced tumor volume and weight which were increased by HMGA1 overexpression." (PMID 33648560, 2021).
tumor (continued). "There was higher expression of the TRIP13 protein in frozen CRCs relative to their matched normal/benign tissues, and TRIP13 overexpression was independent of tumor stage and patient race." (PMID 33037736, 2020). "Downregulation of TRIP13 inhibited HCC cell proliferation, migration, and invasion, promoted apoptosis and cell cycle arrest at S-phase in vitro, and suppressed the formation of tumor in vivo." (PMID 32382578, 2020). "Consistent with data on the mRNA expression of TRIP13, its immunophenotypic expression was independent of tumor stage and patient race, gender, and age." (PMID 33037736, 2020). "TCGA data acquired from UALCAN showed that TRIP13 overexpression was independent of pathologic stage of the tumor." (PMID 33037736, 2020). "Additionally, the levels of cyclinD1 and PCNA in mice tumor tissues of sh-NC, sh-NORAD, and sh-NORAD + anti-miR-495-3p groups were consistent with the TRIP13 mRNA and protein levels." (PMID 32694945, 2020). "D’Silva and colleagues reported that TRIP13 was significantly up-regulated, as analyzed by TCGA and GEO data sets, in tumor tissues and was able to promote non-malignant cells malignant transformation, tumor growth and invasion." (PMID 28424416, 2017). "Our data do not clarify whether TRIP13 directly regulates mitophagy or influences tumor progression through alternative pathways such as DNA repair, metabolic reprogramming, or immune checkpoint modulation." (PMID 41487520, 2025). "In addition, TRIP13 was found to be involved in the activation of AKT/mTOR, Wnt/β-catenin and TGF-β1/SMAD3 signalling pathways to promote the proliferation and metastasis of tumours." (PMID 39187490, 2024). "Thus, we indicated that TRIP13 induces EMT and tumor progression via the PI3K/AKT signaling." (PMID 36268276, 2022). "However, in the subcutaneous tumor formation experiment in vivo, we found that TRIP13 had no obvious effect on tumor growth." (PMID 36268276, 2022). "Additionally, RNA sequencing of CRC cells with TRIP13 knockdown identified COL6A3, TREM2, SHC3, and KLK7 as downstream targets that may have functional relevance in TRIP13‐mediated tumor growth and metastasis." (PMID 33037736, 2020).
cancer (77 papers, 2012 to 2026). A tumor composed of atypical neoplastic, often pleomorphic cells that invade other tissues. "Inhibition of TRIP13 has the potential to address therapeutic challenges in cancer, particularly in therapy-resistant and Rb-deficient cancers." (PMID 40228580, 2025). "Kaplan–Meier survival analysis was performed to investigate the association between clinical outcomes and TRIP13 expression across various cancer types, to detect the effect of TRIP13 on OS, DSS, and PFI." (PMID 40441196, 2025). "Thyroid hormone receptor interaction factor 13 (TRIP13) encodes a member of the highly conserved AAA-ATPase family that contributes to cancer susceptibility." (PMID 40441196, 2025). "The results indicated that TRIP13 overexpression was associated with a poor overall survival, disease-specific survival, and progression-free interval in various cancer types." (PMID 40441196, 2025). "This optimized HTS assay paves the way for discovering novel, potent, and selective TRIP13 inhibitors, ultimately contributing to developing affordable new therapeutic strategies for Rb-deficient and other cancers." (PMID 40228580, 2025). "Overexpression of TRIP13 is a hallmark of cancer cells exhibiting chromosomal instability, especially in certain BrCa with poor prognosis." (PMID 37627217, 2023). "TRIP13 overexpression is common in BRCA1-deficient cancers, confers PARP inhibitor resistance, and correlates with poor prognosis." (PMID 38067275, 2023). "TRIP13 overexpression is common in BRCA1-deficient cancers, which leads to PARP-inhibitor resistance through conformational changes in REV7 and reduces drug sensitivity." (PMID 37529698, 2023). "Mounting evidence indicates that TRIP13 plays an oncogenic role in multiple human cancers, usually associated with poor survival." (PMID 35322916, 2022). "It has been demonstrated that thyroid hormone receptor interactor 13 (TRIP13), which is implicated in progression and metastasis of multiple cancers, acts as an oncogene in EOC development by the modulation of Notch signaling." (PMID 35582386, 2021). "TRIP13 is essential in the spindle assembly checkpoint and is expressed in a number of human cancers, where its reduction has been linked with effects on proliferation and hence therapeutic benefit." (PMID 33208020, 2021). "The delicate balance between MCC assembly and disassembly/degradation pathways, and these pathways’ coordination through space and time, will be important to consider as the contributions to cancer of both TRIP13 loss and overexpression are further studied." (PMID 30341343, 2018). "TRIP13 also appears in cancer-associated molecular signatures, therefore underlining its potential role in cancer." (PMID 26527623, 2016). "Overexpression of TRIP13 is associated with poor clinical outcomes in various cancers." (PMID 40228580, 2025). "TRIP13 (Thyroid Hormone Receptor Interacting Protein 13) belongs to a protein superfamily that is overexpressed in many human cancers and is associated with poor prognosis in cancer patients." (PMID 35346215, 2022). "As EMT is recognized as an important event associated with carcinoma progression, we speculated that TRIP13 might participate in this process." (PMID 31533816, 2019). "MVA syndrome patients with mutations in BUBR1 and TRIP13 are at an increased risk for cancer." (PMID 30035751, 2018). "Two recent reports found that knocking-out TRIP13 from human cancer cell lines or introducing mutations in Pch2, the TRIP13 orthologue in C. elegans, resulted mitotic checkpoint activation defects, arguing that TRIP13 is also involved in establishing or maintaining the mitotic checkpoint." (PMID 28920074, 2016). "In our investigation of TRIP13 expressions in ccRCC, we conducted TRIP13 staining on three adjacent cancer tissues and three ccRCC tissues." (PMID 41487520, 2025). "Pan-cancer analysis was performed to elucidate the prognostic value and oncogenic role of TRIP13, and detect TRIP13 expression levels in diverse cancer types." (PMID 40441196, 2025).
cancer (continued). "Our study provides a valuable tool for discovering novel TRIP13 inhibitors and advances our understanding of the therapeutic potential of targeting TRIP13 in cancer." (PMID 40228580, 2025). "Pan-cancer analysis also shows TRIP13 expression is related to immunocyte infiltration and immune scores in specific cancers." (PMID 41007830, 2025). "Understanding the diverse functions of TRIP13 is crucial for unraveling its implications in physiological and pathological conditions, particularly in cancer, where disruptions in cell division and DNA repair can lead to tumorigenesis." (PMID 41145438, 2025). "This gives a novel mechanism in which MT, through downregulation of TRIP13, slows down aberrant DNA repair and proliferation of cancer cells." (PMID 41145438, 2025). "This emphasizes the need to develop potent and selective TRIP13 inhibitors to complement existing therapies and address therapy-resistant cancers." (PMID 40228580, 2025). "In summary, our results suggested that TRIP13 was a promising prognostic biomarker and a potential predictor of sensitivity to immunotherapy in several malignant tumors and LIHC." (PMID 40441196, 2025). "TRIP13, a promising target for cancer therapy, has been identified as a key regulator of the mitotic checkpoint." (PMID 40228580, 2025). "This optimized assay paves the way for identifying novel and potentially more potent TRIP13 inhibitors, ultimately contributing to developing new therapeutic strategies for cancer." (PMID 40228580, 2025). "The TIMER2.0 program was utilized to analyze variations in TRIP13 expression in various cancer types within the TCGA database." (PMID 40441196, 2025). "We initially examined TRIP13 mRNA expression in various human cancers and their corresponding normal samples from the TCGA database via the UALCAN website." (PMID 41007830, 2025). "In cancer cells, one potential mechanism to prevent Mad2-mediated G1 arrest and mitotic cell death, is regulating Mad2 function via TRIP13." (PMID 40228580, 2025). "Our findings suggest that TRIP13 plays a critical role in regulating the cell cycle, metabolism, and immune response, which ultimately contributes to a worse prognosis in cancer patients." (PMID 40441196, 2025). "Sustained expression of TRIP13, as is frequently observed in cancer, thus provides cancer cells with an alternative DNA repair mechanism through recombination." (PMID 38216586, 2024). "Similar to the differential expression of TRIP13, there are many more (GC) genes that share a similar germline/cancer expression profile." (PMID 38216586, 2024). "A biomarker study involving 165 BC patient samples analyzed the expression levels of four genes (CCNB1, KIF4A, TPX2, and TRIP13) and their association with clinical characteristics, revealing a correlation between elevated CCNB1 expression and cancer stage." (PMID 39795587, 2024). "TRIP13 is reportedly involved in checkpoint signaling, DNA break repair and recombination, and chromosome synapsis, leading to cancer initiation and progression." (PMID 38012658, 2023). "The overexpression of TRIP13 has been observed in many types of cancer and has been identified as an oncogene." (PMID 37740123, 2023). "Thyroid hormone receptor-interacting protein 13 (TRIP13) is a member of the AAA ATPase family, and accumulating evidence indicates that it is overexpressed in multiple cancers and is associated with cancer progression, poor survival, and drug resistance." (PMID 38012658, 2023). "The knockdown of TRIP13 in cancer cells significantly suppressed the malignant phenotypes of the cancer cells (i.e., cell proliferation, invasion, and drug resistance)." (PMID 38067275, 2023). "The increase in expression of TRIP13 in the malignant cells of the stomach was further confirmed by comparing 27 paired cancer and para-neoplastic samples (P < 0.001)." (PMID 37432513, 2023). "Recent studies have reported that various noncoding RNA molecules are involved in the aberrant expression of TRIP13 in cancer cells." (PMID 38067275, 2023).